TMEM156 (transmembrane protein 156)
Synonyms: FLJ23235
Tractability: Antibody: UniProt predicts a signal peptide or a membrane-spanning region.
Gene: Protein-coding gene on chromosome 4 (38,965,999 to 39,032,922, reverse strand). Ensembl gene ENSG00000121895.
Subcellular location: Membrane
Gene Ontology:
Cellular component: membrane
Genetic constraint (gnomAD): Loss-of-function variants: 21 observed, 24.34 expected, observed/expected ratio (o/e) 0.86, 90% interval 0.61 to 1.24. The upper end of that interval is the gene's LOEUF score, 1.24, which puts it in group 5 of 6, group 1 being the genes least tolerant of losing a copy. Missense variants: 279 observed, 290.44 expected, observed/expected ratio (o/e) 0.96, 90% interval 0.87 to 1.06. Synonymous variants: 113 observed, 99.45 expected, observed/expected ratio (o/e) 1.14, 90% interval 0.98 to 1.33.
Homologues: Orthologues: chimpanzee TMEM156 (98% identical), macaque TMEM156 (94% identical), pig TMEM156 (77% identical), dog TMEM156 (73% identical), rabbit TMEM156 (73% identical), guinea pig TMEM156 (69% identical), rat Tmem156 (55% identical), mouse Tmem156 (53% identical).
Diseases named in the same sentence as TMEM156 in open-access papers:
TMEM156 is named in the same sentence as 16 diseases in open-access papers, as found by Europe PMC text mining. Sharing a sentence is not in itself a finding about the gene and the disease. The quoted sentences say what the papers report.
liver cancer (3 papers, 2015 to 2023). An epithelial or non-epithelial malignant neoplasm that arises from the liver. "A previous study also reported that the relative amount of TMEM156 mRNA was higher in various cancer cell lines such as prostate, breast, and liver cancers." (PMID 37887755, 2023). "While no staining was detected in normal liver tissue (n = 8), liver cancer samples (n = 16) showed significant induction of TMEM156 (P < 0.001)." (PMID 26427334, 2015).
breast carcinoma (2 papers, 2020 to 2021). "In conclusion, we identified and constructed a 5-gene signature (GP6, MAK, DCTN2, TMEM156, and FKBP14) prognostic model to predict prognosis in breast cancer patients." (PMID 34722557, 2021).
viral infection (2 papers, 2017 to 2021). "However, when the patients from GEO were divided depending on HPV status, the association between longer OS time and TMEM156 expression was indicated for only HPV(+) patients (and not for HPV(−)), which proves the connection of this TMEM with a viral infection." (PMID 34638224, 2021).
cancer (6 papers, 2015 to 2023). A tumor composed of atypical neoplastic, often pleomorphic cells that invade other tissues. "What is more, genes negatively correlated with TMEM156 are linked with RHO GTPase effectors, which results in a poorer response to receptor activation, thus reducing cancer cell proliferation, survival, and migration." (PMID 34638224, 2021). "However, the function of TMEM156 mRNA in cancer has been poorly explored." (PMID 37887755, 2023). "In addition, the role of TMEM156 in cancer is poorly understood." (PMID 34638224, 2021). "The other genes that were examined, TMEM156 and C11orf68, to our knowledge were never shown to have biochemical or cellular role that could be linked to cancer." (PMID 26427334, 2015). "What is more, the gene sets enriched in HNSCC patients with high TMEM156 expression are similar to those with high expression of TMEM173, which may suggest a similar function in cancer development and progression." (PMID 34638224, 2021). "CXCL8 and LAPTM5 proteins have been reported to promote cell activity, TMEM156 and LGALS1 proteins enhance cell invasion, VIM and LGALS1 proteins induce cell migration, FABP5 and SRGN proteins activate cancer metastasis, and the DEFB4A protein regulates immunity in human cancers." (PMID 35632763, 2022). "To provide a proof of principle that the list of genes that are commonly hypomethylated and induced in 3 invasive cancer cell lines could serve as a source for discovery of new genes involved in invasiveness, we picked four genes, C11orf68, G0S2, SHISA2 and TMEM156." (PMID 26427334, 2015).
tumor (2 papers, 2021 to 2022). "Th1 cells, which stimulate cytotoxic T lymphocytes (CTLs) to facilitate tumor rejection, are present to a greater extent in patients with high expression of TMEM156 and TMEM173." (PMID 34638224, 2021). "The expression of TMEM17, TMEM97, TMEM140, TMEM156, TMEM173, and TMEM206 show significant correlation with immune, stromal, and ESTIMATE scores which indicates a strong association between those TMEMs and immune response inside a tumor microenvironment." (PMID 34638224, 2021). "Oppositely to TMEM156, TMEM173, and TMEM213, patients with higher ANO1 expression have a lower fraction of lymphocytes in the tumor microenvironment." (PMID 34638224, 2021). "That may suggest the important role of TMEM213 in the immune response against the tumor; however, these results are not as conclusive as in the case of TMEM156 and TMEM173." (PMID 34638224, 2021).
TMEM156 also shares sentences with these, for which no sentence is quoted: clear cell renal cell carcinoma (1 paper); colorectal cancer (1); esophageal cancer (1); hepatocellular carcinoma (1); lung carcinoma (1); melanoma (1); non-small cell lung carcinoma (1); ovarian carcinoma (1); pancreatic cancer (1); prostate carcinoma (1); stomach cancer (1).